ALB (albumin)
Diseases named in the same sentence as ALB in open-access papers (continued):
Sharing a sentence is not in itself a finding about the gene and the disease.
tumor (continued). "In contrast, a first-in-human application of [177Lu]Lu-PSMA-ALB-56, a PSMA radioligand modified with a p-tolyl-butanoyl entity as an albumin binder, revealed similar salivary gland accumulation as [177Lu]Lu-PSMA-617 and, therefore, a favorable tumor-to-salivary gland dose ratio." (PMID 36428743, 2022). "Our protein library contained 17 proteins in the context of an infection (CMV, HPV, EBV, HBV, mumps, LPS), tumor and cellular stress response (HSP27, HMGB1, CRT, HO-1, HO-2, IL8), autoimmunity (insulin, collagen, vimentin, albumin) or others (ovalbumin, bovine serum albumin)." (PMID 36429087, 2022). "Low scores indicate a decrease in BMI and albumin with an increase in NLR, which might be responsible for aggressive tumour biology, cancer progression, and poor prognosis." (PMID 36614896, 2022). "Pretreatment blood examinations for C-reactive protein (CRP) and albumin levels; neutrophil, lymphocyte, and white blood cell (WBC) counts; and neutrophil/lymphocyte (N/L) ratio were investigated and correlated with tumor size, tissue grade, and maximum standardized uptake value (SUVmax)." (PMID 36181081, 2022). "Comparing with the previous 10 years from 2000-2009, the biochemical features in PHPT patients, such as serum PTH, albumin-corrected Ca, ALP concentrations all became lower; and tumor size to be smaller; kidney function and BMDs turned to be better in recent 10 years from 2010-2019." (PMID 35784571, 2022). "In addition, CCI; ALB levels; Alcohol consumption; PNI and CNC before treatment; tumour site; disease stage; T stage." (PMID 36531036, 2022). "Systemic nonantiproliferative tumor therapies (bisphosphonates, human albumin, and growth factors) to alleviate symptoms are used in the hospices surveyed, for the most part, rarely or never." (PMID 36059908, 2022). "Overall, patients with a higher De Ritis ratio level had lower BMI and albumin levels, but a higher proportion of ALBI grade; had HBV DNA content ≥103 copies/ml, AFP level ≥400 ng/ml, and main tumor size ≥5 cm; and presented with BCLC stage B and C, and tumor thrombus." (PMID 35664791, 2022). "Our newly developed score model, which incorporated, in addition to patient factor sarcopenia, tumor number, tumor size, major venous thrombosis, serum AFP, and albumin into consideration, could effectively predict patient survival after TACE." (PMID 36248997, 2022). "The total protein (TP), albumin (ALB), and alkaline phosphatase (ALP) levels in tumor-bearing mice were relatively lower compared with those of mice in the normal group due to the pathological state (p < 0.05 or p < 0.01), and did not change even after treatment." (PMID 35281908, 2022). "Interestingly, the high abundance identifies were consistent both in the tumor and normal tissues in EESCC and EDAC at the protein level, including HBB, HBA1, HBD, ACTB, ALB, etc.." (PMID 35397555, 2022). "In this setup, the albumin NPs can target the GBM cells and tumor vessel endothelial cells to regulate the TME, while the disulfiram/copper complex induced ICD to promote antigen presentation and regorafenib repolarized the M2 macrophages to assume the M1 phenotype." (PMID 36311702, 2022). "The preoperative clinical laboratory tests were as follows: tumor markers: preoperative CA19-9 > 27 U/mL (52.4%), preoperative CEA > 5 ng/mL (22.3%); liver function markers: ALB ≥ 40 g/L (79.0%), TBIL > 21 μmol/L (11.5%), AST > 40 U/L (9.6%), and ALT > 50 U/L (8.9%)." (PMID 33648470, 2021). "In these cases, cells will not be able to process albumin once it is internalized; instead, it degrades, providing the tumor with nutrients and promoting its growth." (PMID 34638659, 2021). "The model incorporated tumor size and number, alpha fetoprotein (AFP) level (ng/ml), protein induced by vitamin K absence (PIVKA) level (mAU/ml), lymphocyte count (/ul), serum albumin level (g/dl), and ascites, and a nomogram was developed to predict patient survival." (PMID 33903282, 2021).
tumor (continued). "Tumour tissues were then subjected to immunohistochemistry to assess cell differentiation, as indicated by the cytoplasmic‐to‐nuclear ratio and markers such as CYP3A4, HNF4α and albumin." (PMID 33179425, 2021). "Tumor size (HR, 1.479; 95% CI, 1.114–1.965; P = 0.007), TNM stage (HR, 1.642; 95% CI, 1.238–2.177; P = 0.001), albumin (HR, 1.547; 95% CI, 1.194–2.003; P = 0.001), and ALRI (HR, 1.703; 95% CI, 1.339–2.166; P < 0.001) were identified as independent predictive factors of DFS." (PMID 34295811, 2021). "In our study we took into account NLR and LDH, in addition to blood albumin concentration, another well-established prognostic factor in cancer patients regardless of tumor type and oncological treatment, embedded together in the GRIm-Score." (PMID 33801320, 2021). "Although age, tumor grade, and stage are sufficiently available in the TCGA database, other commonly used features such as preoperative albumin, Ashkenazi ancestry, and maximum diameter of residual tumor (ie, degree of success of surgical resection) were not." (PMID 34181012, 2021). "The signature selected by the best performing model included the following seven predictors: albumin levels; Ki-67 staining; LDH below or above the ULN; lymphocytes (L); platelet levels; tumor infiltration assessed by morphology and immunohistochemistry on bone marrow biopsy (BMInf); and B-symptoms." (PMID 35008361, 2021). "Albumin-based nanoparticles are emerging as suitable candidates for plasmid delivery in cancer therapy because of the high efficiency of DNA transfection into tumor cells, non-toxicity, and biodegradability imparted by albumin molecules." (PMID 34298666, 2021). "The univariate analysis showed that age ≥ 85 years, CCI score ≥ 5, male sex, low BMI, low albumin, high WBC, low Hb, high CEA, high NLR, low PNI, low GNRI, T4 tumor grade, high number of lymph node metastases, poor histological features and grade, and emergency surgery were associated with poor OS." (PMID 34831005, 2021). "Immunohistochemical analyses showed an absence of resistant colonies and an increase in CYP3A4 and albumin expression in drug combination‐treated tumours." (PMID 33179425, 2021). "For example, ultrasound can be used to unbind anti-tumor drugs such as paclitaxel from the albumin (> 90 % binding to albumin) to enhance its delivery to a tumor region without increasing systemic dose." (PMID 34020595, 2021). "A bovine serum albumin (BSA) model compound was used to increase the cisplatin incorporation; then, it was successfully substituted by a iRGD tumour penetrating peptide that might provide a targeting function of the nanoparticles." (PMID 35052723, 2021). "Meanwhile, tumor depth, tumor stage, FVC, and albumin were independent prognostic predictors." (PMID 34011041, 2021). "This study demonstrates, for the first time, a severely different accumulation and retention pattern in various organs with much less tumor accumulation and significant accumulations in liver the albumin-AuNP-conjugate when compared to the control PFT-Hcy-HSA-Cy7-pTFT." (PMID 33451058, 2021). "In addition, tumor size, BCLC-B sub-classification, AFP and ALB levels, as well as number of lesions exhibited the highest VIMP and lowest minimal depth, indicative of strong predictive performance." (PMID 33738252, 2021). "Moreover, we checked the expression of contamination markers albumin, calnexin and Gm130 as well as another EV marker TSG101 in both EVs and tumor tissues by Western Blot as a quality control of EV isolation." (PMID 33391510, 2021). "Serum GGT levels and especially combination serum GGT plus albumin levels, were significantly associated both with HCC patient survival and tumor aggressiveness characteristics, regardless of AFP levels in a large Turkish cohort." (PMID 34540270, 2021).
tumor (continued). "GNRI was composed of serum albumin level and body weight ratio [actual body weight (ABW)/ideal body weight (IBW)], and the ratio of ABW and IBW can more objectively reflect the weight changes in oncology patients due to tumor depletion." (PMID 34381731, 2021). "HBV integrations that disrupt the ALB gene have been reported in multiple studies, and it has been shown that they more commonly occur in non-tumor samples than in tumor samples." (PMID 34442866, 2021). "At diagnosis, most patients presented with comparable biochemical levels of serum proteins (transferrin, albumin, ferritin, prealbumin and reactive C protein (RCP)), lipids (total and fractionated cholesterol) and lymphocytes, considering the primary tumor site." (PMID 35008278, 2021). "The majority of tumour cells in the drug combination‐treated tumours had morphologic evidence of the terminal hepatocyte differentiation and exhibited a uniformly higher expression of CYP3A4 and albumin staining throughout the tissue section." (PMID 33179425, 2021). "Albumin was originally thought to bind to SPARC (secreted protein acidic and rich in cysteine) in the tumor microenvironment, however more recent experimental data revealed that increased delivery and antitumor activity of nab-paclitaxel does not depend on the interaction with SPARC." (PMID 34282781, 2021). "Similar results were also obtained with [18F]F-fluorodeoxyglucose-folate and [47Sc]Sc-DOTA-folate containing an albumin binder, also showing a higher tumor-to-kidney ratio than conjugates without albumin binding properties." (PMID 35056911, 2021). "Univariate analysis revealed that albumin, total bilirubin, ALBI grade, alpha-fetoprotein (AFP), greatest tumor size, macroscopic vascular invasion, extrahepatic metastasis, BCLC stage, GPS score, mGPS score, Hs-mGPS, NLR score, PLR score, PNI score, SII score, and LCR score were associated with OS." (PMID 33589570, 2021). "We demonstrated that chronological age, poor liver function with higher MELD score, tumor size, lower albumin and platelet level, higher cancer stage, non-response to the TACE, as well as MDVA were major risk factors for poor survival outcomes." (PMID 34715813, 2021). "Human serum albumin (HSA) is an appealing material for developing novel nanomedicines as it has a high drug loading ability, self-assembling properties, long half-life, and preferential uptake by tumor and inflamed tissues." (PMID 35056915, 2021). "Serum albumin is stable, biocompatible, nontoxic, non-immunogenic, and can accumulate at tumor tissues or sites of inflammation attributing to the interaction of albumin with gp60 receptor and SPARC." (PMID 34869202, 2021). "AFP, alpha‐fetoprotein; ALB, albumin; ALT, alanine aminotransferase; AST, aspartate transaminase; CI, confidence interval; HBsAg, hepatitis B surface antigen; SNRPC, expression in tumor nucleus; TBIL, total bilirubin." (PMID 33934562, 2021). "The correlation analysis of the expression of GSTA2 and the identified ROS-associated genes using the LIHC database in the GEPIA web server revealed that the expression level of GSTA2 was significantly correlated with ALB, TPO, APOE, MBL2, and FTH1 in the tumor tissues." (PMID 34290233, 2021). "Compared to SR, the HCC patients with tumor size < 3 cm, single tumor, albumin-bilirubin (ALBI) grade 1 and those without CSPH who received RFA-TACE treatment had higher risks of recurrence in the univariate analysis." (PMID 33685409, 2021). "The results show that the longest survival (median 26 months) was for the combination of absent PVT and absent tumor multifocality plus normal blood albumin levels (>3.5 g/dL), and this was used as the reference univariate hazard ratio." (PMID 33546234, 2021).
tumor (continued). "Multivariate analysis was performed by using several factors of age <77 years old, albumin level ≥35 g/L, ICGR15 <20 %, Child-Pugh classification A, AFP <100 μg/L, PIVKA-II level <100 mAU/mL, and maximum tumor size <5 cm, which were p<0.1 in univariate analysis." (PMID 33112547, 2020). "However, we did not observe any associations between serum lncRNA and gender, HBsAg, tumor size, tumor number, AST, TP, and ALB." (PMID 32733618, 2020). "Cox regression revealed that a tumour number equal or greater to two (HR 1.54), AFP > 400 μg/l (HR 1.14), serum albumin < 3.6 g/dl (HR 1.63) and total bilirubin > 0.9 mg/dl (HR 1.58) were independent risk factors in our population, excluding patients with subsequent LTX." (PMID 32125515, 2020). "GNRI values were significantly associated with age (p < 0.001), BMI (p < 0.001), RBC (p < 0.001), albumin (p < 0.001), CRP (p < 0.001), tumor size (p < 0.001), operative procedure (p = 0.043), depth of tumor (p < 0.001), pathological stage (p < 0.001), and intraoperative blood loss (p = 0.029)." (PMID 32595832, 2020). "In multivariate analyses, serum albumin (hazard ratio [HR], 2.498; p = 0.0043), GNRI (HR, 1.941; p = 0.0181), pathological tumor-node-metastasis (pTNM) stage (HR, 3.884; p < 0.0001), and tumor differentiation (HR, 2.307; p = 0.0066) were independent prognostic factors for CSS." (PMID 32754301, 2020). "APPs, such as alpha 1-acid glycoprotein (AGP), transferrin (TRF), albumin (ALB) and C-reactive protein (CRP), are produced by hepatocytes as part of the innate acute phase response to trauma, infection, stress, neoplasia and inflammation, and their expressions are elevated in diarrhea." (PMID 32722717, 2020). "Expression of UBC in non-tumour tissues was negatively correlated with AST and total bilirubin levels (Spearman's rho= -0.39 and -0.31; P=0.017 and 0.065, respectively), but positively correlated with albumin levels (Spearman's rho= 0.36; P=0.03)." (PMID 32132870, 2020). "Considering the normal values, it can be observed that the animals of the five groups showed a marked decrease in serum albumin, but not in the rest of the parameters measured, which were not affected by the tumor or by the treatment with GM1-Ptx." (PMID 32576898, 2020). "The baseline characteristics of patients in the HAIC group and the symptomatic treatment group were similar in age, sex, tumor size, tumor number, ALT level, albumin level, bilirubin level, presence of ascites, Child's classification, Okuda stage, CLIP stage, BCLC substage and AJCC stage." (PMID 32769883, 2020). "Nab-PTX is associated with increased uptake by utilising the endogenous albumin pathways of gp60- and Cav-1-mediated endovascular transcytosis and binding between albumin and SPARC, which enables the drug to more thoroughly permeate the tumour." (PMID 32532230, 2020). "Drug-loaded albumin NPs were recently found to target SPARC (secreted protein acidic and rich in cysteine) and gp60 (glycoprotein 60), which are overexpressed in glioma and tumor vessel endothelia." (PMID 33419339, 2020). "Additionally, the guiding effects of tumor size, AFP, CEA, CGA, and albumin on prognosis were limited." (PMID 32590784, 2020). "In the discovery study cohort, albumin was significantly increased and immunoglobulins (IgG, IgA, IgM) were slightly elevated in PCNSL tumor patients in contrast to tumor-free control patients and confirmed that in 58% of the analyzed PCNSL patients, the BBB is disrupted." (PMID 32610669, 2020). "As opposed to dynamic monitoring circulating tumor cells or DNA, serum albumin level has the advantages of ease of use, ready availability, and low cost." (PMID 33585232, 2020). "It is discovered that rational incorporation of a dye into the albumin-based nanoparticle could help improve the photoluminescence quantum yield (PLQY) of the dye, which benefits the precise tumor imaging and therapy with external stimulus." (PMID 32183838, 2020).
tumor (continued). "GEM-HSA-NP is a gemcitabine-loaded albumin nanoparticle; using patient-derived xenograft models, this nanoparticle has been shown to be more effective than gemcitabine in inhibition of tumour growth, irrespective of expression levels of hENTs." (PMID 35582220, 2020). "The albumin-bound ABD-based protein revealed, in early in vivo mapping, heterogeneities in the uptake in different sub-regions of the same tumor, between different tumor models, over time as well as in response to a vasodilatory challenge." (PMID 32960353, 2020). "PNI and GPS consist of albumin and lymphocytes or C-reactive protein (CRP), which may reflect the balance between the pro-tumor inflammatory status and nutritional status." (PMID 33129309, 2020). "Selective coupling of chemotherapeutics to human serum albumin (HSA), the most abundant blood serum protein, has proved to be a successful strategy for enhanced tumour targeting because HSA can act as a long-circulating delivery vehicle which accumulates passively in the tumour tissue." (PMID 31945705, 2020). "Preoperative CA125, albumin, and D-dimer levels; neutrophil to lymphocyte ratios (NLR); and monocyte to lymphocyte ratios were significantly correlated with FIGO stage, residual tumor, and platinum response." (PMID 32771026, 2020). "The result showed that albumin, globulin, CEA, CA199, LMR, PLR, NLR, vascular invasion, nerve invasion, TNM, tumor size, and GGT were significant indicators, and p-values of variables less than 0.05 in univariate analysis were included in the multivariate analysis." (PMID 32426277, 2020). "Due to the lack of a designated albumin binder and thus extremely fast clearance from background organs, tumor-to-background ratios of [177Lu]Lu-PSMA-617 were higher than those of the albumin-binding radioligands at all investigated timepoints." (PMID 32486054, 2020). "The isomers were evaluated in vitro (IC50, binding to and internalization into LNCaP cells, binding to human serum albumin (HSA)) and biodistribution studies in LNCaP tumor-bearing SCID mice were performed and compared to the diastereomeric mixture [18F, natGa]rhPSMA-7." (PMID 33284394, 2020). "While the cellular pathway of albumin uptake was not identified, this study indicated that albumin was taken up by tumour tissue and catabolized in the lysosome." (PMID 30967008, 2019). "In addition to RIP1‐Tag5 and 4T1 tumours, TNFα‐CSG (5 daily i.v. injections of 5 μg) also improved immune T‐cell infiltration into ALB‐Tag HCC (Fig EV3D)." (PMID 31709774, 2019). "Together, these experiments demonstrated elevated macropinocytosis and albumin catabolism in tumours as compared to adjacent non-cancerous tissue, confirming earlier observations in cultured cancer cell lines." (PMID 30967008, 2019). "Finally, seven essential variables including tumor size, tumor number, AFP level, PIVKA‐II level, lymphocyte count, albumin level, and presence of ascites were identified as prognostic factors with statistical significance." (PMID 31290618, 2019). "After matching, the laparoscopic group and open group were well balanced in aspects of age, gender, BMI, preoperative HGB, preoperative albumin, ASA score, comorbidity, previous abdominal surgery, tumor location, tumor differentiation, TNM stage, and preoperative CEA." (PMID 31521147, 2019). "Serum levels of liver function such as albumin and bilirubin as well as the tumor markers did not correlate with survival in our study." (PMID 31881761, 2019). "This time course of the fluorescence intensity perfectly reflects the mechanism of TPS uptake by tumor cells, which is considered as follows: TPS, a water-soluble drug, is conjugated with albumin immediately after intravenous injection, and the conjugate circulates in the bloodstream." (PMID 30949484, 2019). "As there is a positive correlation between tumor-infiltrating lymphocytes and ALC or the albumin level, PNI might influence the survival outcome through an immunological mechanism." (PMID 31217896, 2019).